TBK1 (TANK binding kinase 1)
Diseases named in the same sentence as TBK1 in open-access papers (continued):
Sharing a sentence is not in itself a finding about the gene and the disease.
HCMV infection (10 papers, 2016 to 2025). "Taken together, these findings demonstrate that latent HCMV infection activates the STING/p-TBK1/p-IRF3 signalling cascade but impairs p-IRF3 nuclear translocation." (PMID 40872823, 2025). "The cGAS/STING/TBK1 pathway has been shown to mediate an IFN response to HCMV infection in fibroblasts (10, –, 14), endothelial cells, macrophages, and dendritic cells." (PMID 34903048, 2021). "We conclude that UL138 inhibits the cGAS/STING/TBK1 innate immune response in 293T cells, in fibroblasts (in which HCMV infection is lytic), and in THP-1 cells (in which HCMV infection is latent)." (PMID 34903048, 2021). "Our work has identified the first inhibitor of cGAS/STING/TBK1 that is expressed and functions during latent HCMV infections within incompletely differentiated myeloid cells." (PMID 34903048, 2021). "In this study, we investigated whether latent HCMV infection modulates the STING/p-TBK1/p-IRF3 pathway to influence CD34+ cell differentiation." (PMID 40872823, 2025). "Notably, although the majority of tegument UL35 localizes to the nucleus during HCMV infection, a fraction of UL35 was detected outside the nucleus, which would be in line with cytoplasmic TBK1 or associated factors being its potential target." (PMID 32466380, 2020). "The cGAS-STING pathway may play an important role in the type I IFN pathway upon HCMV infection because KD of either cGAS or STING strongly abolishes activation of TBK1 and IRF3." (PMID 29018427, 2017). "Taken together, these data suggest that the role in promoting IFNB1 and VPA-responsive IE gene expression downstream of cGAS/STING during HCMV infection is specific to TBK1 and that IKKε may instead restrict viral gene expression during HCMV infection of incompletely differentiated myeloid cells." (PMID 38932169, 2024). "We conclude that TBK1 activity is required for IFN-I and VPA-responsive IE gene expression during HCMV infection in THP1 monocytes." (PMID 38932169, 2024). "Given the reported roles of USP1 in stabilizing TBK1 and of UL138 in inducing STING for degradation outside the context of infection, we analyzed total and phosphorylated levels of TBK1 and STING during HCMV infection." (PMID 37289831, 2023). "We used a return-of-function approach as a first examination of the effects of UL138 on the cGAS/STING/TBK1 pathway and IFN-β mRNA accumulation during HCMV infection." (PMID 34903048, 2021). "With a series of luciferase reporter assays and the analysis of signaling kinetics upon HCMV infection, we observed that UL35 downmodulates PRR signaling at the level of the key signaling factor TANK-binding kinase 1 (TBK1)." (PMID 32466380, 2020). "While IFI16 induces cytokines, only cGAS activates STING/TBK-1/IRF3 and apoptotic responses upon HSV-1 and HCMV infections." (PMID 27935834, 2016). "Since the STING/p-TBK1 pathway normally activates p-IRF3, leading to its translocation into the nucleus and subsequent transcription of type I IFN genes, it is possible that latent HCMV infection modulates this process." (PMID 40872823, 2025). "HCMV infection of human foreskin fibroblasts induced NOD2, the downstream receptor-interacting serine/threonine-protein kinase 2 (RIPK2), resulting in phosphorylation of TANK-binding kinase 1 (TBK1) and interferon regulatory factor 3 (IRF3)." (PMID 26830977, 2016). "Our data, however, suggest that TBK1 and IKKε are not redundant for either IFNβ induction or VPA-responsive viral IE gene expression, at least not in the context of HCMV infection in THP1 cells." (PMID 38932169, 2024).
Hepatic steatosis (10 papers, 2022 to 2025). Steatosis is a term used to denote lipid accumulation within hepatocytes. "Inhibiting TBK1 by administering amlexanox or knocking out the TBK1-encoding gene significantly alleviated hepatic steatosis by decreasing fat accumulation, lipogenic gene expression, proinflammatory cytokine levels and macrophage infiltration in the livers of HFD-fed mice or ob/ob mice 80,81." (PMID 38164186, 2024). "Phosphorylation of TBK1(Ser172), a marker for its kinase activity, is increased during the early stages of hepatic steatosis—likely in response to inflammatory cues." (PMID 41282122, 2025). "We note that numerous studies have demonstrated that treatment with the TBK1/IKKε inhibitor amlexanox ameliorates hepatic steatosis, inflammation, and fibrosis in MASLD models." (PMID 41282122, 2025). "Elevated TBK1 phosphorylation, a downstream target of STING, has been observed in HFD-fed mice, and inhibiting TBK1 via amlexanox or gene knockout significantly reduced hepatic steatosis, inflammation, and macrophage infiltration." (PMID 39669992, 2024). "Blocking the IKK ɛ and TBK1 pathways can significantly reduce the inflammatory factors produced by pro-inflammatory cells such as TNF- α and MCP-1, thereby improving insulin sensitivity and reducing liver steatosis." (PMID 38436022, 2024). "As such, hepatocyte-specific deletion of Tbk1 in mice results in fatty liver disease due to a lack of TBK1-mediated sequestration of ACSL1 in mitochondria, thereby causing a defect in the β-oxidation of fatty acids." (PMID 35395857, 2022). "In addition, absence of TLR4 downstream molecules IKKε and TBK1, or treatment with an IKKε- and TBK1-specific inhibitors showed a protective effect against hepatic steatosis." (PMID 37020586, 2023).
dementia (9 papers, 2018 to 2026). Loss of intellectual abilities interfering with an individual's social and occupational functions. "FTD, the second most common form of pre-senile dementia, can also be caused by genetic mutations in other genes, including TANK-binding kinase 1 (TBK1)." (PMID 32848189, 2020). "In summary, we describe a novel TBK1 mutation in a patient who presented with a CBS–PNFA overlap and who had a family history of dementia and ALS." (PMID 31160356, 2019). "In conclusion, we show that TBK1 mutations can be a cause of an atypical parkinsonian syndrome and screening should be considered in CBS patients with a family history of dementia or ALS." (PMID 31160356, 2019). "Approximately one quarter of TBK1 mutation carriers were diagnosed with pure FTD, a few with unspecified dementia and above one fifth with a combination of ALS and FTD or unspecified dementia." (PMID 30534373, 2018).
gastric cancer (9 papers, 2017 to 2025). A primary or metastatic malignant neoplasm involving the stomach. "Furthermore, co-expression of IKKε and TBK1 was associated with more differentiated histology, namely, intestinal-type gastric cancer." (PMID 27145266, 2017). "In the current study, we demonstrated that MK1775 increased the accumulation of cytosolic dsDNA and activation of TBK1 phosphorylation in MUS81-deficient gastric cancer cells, indicating that MK1775 could activate the innate immune response via the cGAS/STING pathway." (PMID 34625086, 2021). "It activates the TBK1-IRF1 and TBK1-mTOR pathways, thus enhancing the transcription of PD-L1 and promoting the escape of gastric cancer cells from immune surveillance." (PMID 39048965, 2024). "We also found that MK1775 triggered the phosphorylation of TBK1 efficiently in MUS81 knockdown gastric cancer cells." (PMID 34625086, 2021). "In a multivariate binary logistic regression model, intestinal histologic type by Lauren classification and early AJCC stage were significant predictors for expression of IKKε and TBK1 proteins in gastric cancer." (PMID 27145266, 2017). "Our study sought to investigate IKKε and TBK1 expression in gastric cancer and their role in prognosis." (PMID 27145266, 2017). "In our study, the multivariate binary logistic regression model was applied to determine prediction factors for IKKε+/TBK1+ expression in gastric cancer." (PMID 27145266, 2017). "To investigate overexpression of IKKε and TBK1 in gastric cancer and their relation to clinicopathologic factors, we performed immunohistochemical staining in 1,107 resected gastric cancers using a tissue microarray approach." (PMID 27145266, 2017). "We identified IKKε and TBK1 expression in 13.6% and 3.4% of gastric cancers, respectively, and co-expression of IKKε and TBK1 in 1.5% of cases." (PMID 27145266, 2017). "To investigate overexpression of the IKKε and TBK1 proteins in gastric cancer and their relationship with clinicopathologic factors, we performed immunohistochemical staining using a tissue microarray." (PMID 27145266, 2017). "Expression of IKKε and TBK1 was observed in 13.6% (150/1107) and 3.4% (38/1107) of gastric cancer patients, respectively." (PMID 27145266, 2017). "In conclusion, this is the first large-scale study investigating the relationships between expression of IKKε and TBK1 and clinicopathologic features of gastric cancer." (PMID 27145266, 2017). "We identified expression of IKKε in 150 (13.6%) and TBK1 in 38 (3.4%) gastric cancers." (PMID 27145266, 2017). "Thus, testing for IKKε and TBK1 overexpression should be considered in certain patients, such as those with intestinal-type gastric cancer." (PMID 27145266, 2017). "The frequency of IKKε and TBK1 co-expression was relatively high in early T stage, suggesting that alteration of IKKε and TBK1 could be more involved in the development of gastric cancer." (PMID 27145266, 2017). "This discrepancy could be due to the differing roles of IKKε and TBK1 in gastric cancer or the small number of positive cases." (PMID 27145266, 2017). "Knockdown of TRIM65 inhibits gastric cancer cell growth and aggressiveness by inhibiting PPM1A ubiquitination and blocking TBK1 phosphorylation." (PMID 40936722, 2025). "Lee et al35 analyzed the expression levels of IKBKE and TBK1 using tissue microarray samples obtained from 1107 gastric cancer patients and found upregulation of IKBKE in 150 samples (13.6%) and upregulation of TBK1 in 38 samples (3.4%)." (PMID 31733040, 2020). "In gastric cancer with high TRIM28 expression: TRIM28 stabilizes PD-L1 protein by inhibiting PD-L1 ubiquitination and promoting its SUMOylation; meanwhile, it increases PD-L1 abundance by activating the TBK1 pathway, exacerbating immune evasion." (PMID 40936722, 2025). "However, the expression of IKKε and TBK1 in gastric cancer and their role in prognosis have not been studied." (PMID 27145266, 2017).
gastric cancer (continued). "Thus far, the expression of IKKε and TBK1 in gastric cancer and their role in prognosis have not been studied." (PMID 27145266, 2017).
primary open-angle glaucoma (9 papers, 2014 to 2024). "For example, specific genes, such as CYP1B1, which is linked to primary congenital glaucoma, and MYOC, OPTN, and TBK1, which are associated with primary open-angle glaucoma (POAG), are highlighted as critical markers for assessing genetic risk." (PMID 39840199, 2024). "In the light of the close relationship between CYLD and apoptosis, it could be speculated that the deregulation of the Optn/TBK1/CYLD axis could be involved in the neuronal cell death observed in Open Angle Glaucoma and familial ALS, independently of its effect on the antiviral immune pathway." (PMID 25923723, 2015).
prostate carcinoma (9 papers, 2019 to 2025). A carcinoma that arises from epithelial cells of the prostate gland. "Moreover, palbociclib promotes the STING-TBK1 pathway in Rb-deficient prostate cancer cells by dephosphorylating TBK1." (PMID 41463246, 2025). "From these data, we conclude the growth inhibitory effect of RBN2397 in prostate cancer cells is separable from its effects on IFN signaling that are linked to the kinase activities of JAK1/2 and TBK1." (PMID 37077937, 2023). "For instance, the knockdown of TBK1 (TANK binding kinase 1), a negative regulator of mTORC1, decreases prostate cancer stem-like cell number and drug resistance, while rapamycin induces cell cycle arrest and enhances chemoresistance." (PMID 35216401, 2022). "In prostate cancer Docetaxel-resistant cells, low expression of LINC01085 enhances TBK1 interaction with GSK3β and accelerates phosphorylation of TBK1 at Ser-172, thereby increasing expression of PD-L1 and NF-κB." (PMID 37662910, 2023). "To this end, we employed specific inhibitors to TBK1 (GSK8612; GSK) and JAK1/2 (Ruxolitnib; Ruxo) in prostate cancer cell lines and induced PARP7 via AHR (PC3, DU145) and AR (PC3-AR)." (PMID 37077937, 2023). "Because IRF3 can also regulate the cell cycle, we queried whether TBK1 activity and IFN signaling are involved in the growth-inhibitory effects of RBN2397 in prostate cancer cells." (PMID 37077937, 2023). "Finally, we used chemical inhibitors to TBK1 and JAK1/2 to show that RBN2397 inhibition of prostate cancer cell growth can be distinguished from the RBN2397 effect on PARP7 regulation of type I IFN signaling." (PMID 37077937, 2023). "It negatively regulates tank binding kinase 1 activity, which restrains phosphorylation and activation of the transcription factor IRF3, inhibiting androgen‐induced ADP‐ribosylation of the androgen receptor in prostate cancer and trapping PARP7 within the nucleus." (PMID 38342608, 2024).
sarcoma (9 papers, 2017 to 2023). A usually aggressive malignant neoplasm of the soft tissue or bone. "The most common genes involved are Chromosome 9 open reading frame 72 (C9orf72), SOD1, TDP-43, fused in sarcoma and TANK-binding kinase 1, which together cause 15% of the ALS cases." (PMID 36751500, 2022). "Our analysis also revealed two previously identified ALS-associated genes TBK1 (TANK binding kinase) (FDR = 0.063) and FUS (fused in sarcoma; FDR = 0.155) with a marginal statistical significance." (PMID 36835433, 2023). "The analysis also revealed two previously identified ALS-associated genes TBK1 (TANK binding kinase) (FDR = 0.063) and FUS (fused in sarcoma; FDR = 0.155), with marginal statistical significance." (PMID 36835433, 2023). "Analysis of our RNA-Seq data revealed that no major pathway components, including Cgas, Sting, Irf3, or Tbk1, were downregulated in Atrx-deleted mouse sarcomas relative to their Atrx WT control either in vitro or in vivo." (PMID 37200088, 2023). "Moreover, the findings of the pan-cancer analysis suggested that increased levels of TBK1 expression were associated with worse OS in ESCA, KIRC, LUAD, Pheochromocytoma and Paraganglioma (PCPG), and THYM; however, they were linked to better OS in BLCA, sarcoma (SARC), and thyroid carcinoma (THCA)." (PMID 33679751, 2021).
Alzheimer disease (8 papers, 2019 to 2025). A progressive, neurodegenerative disease characterized by loss of function and death of nerve cells in several areas of the brain leading to loss of cognitive function such as memory and language. "Alzheimer's disease (AD) due to TBK1 gene mutation is extremely rare, and only one case has been reported in China so far." (PMID 36408501, 2022). "In contrast, peptides deriving from microtubule-associated protein tau, presenilin 2 and serine/threonine-protein kinase TBK1 were exclusively reported to bind MHC molecules encoded by the HLA-DRB1 1501 allele, a recently-identified susceptibility gene for late onset Alzheimer's disease." (PMID 31824497, 2019). "Yet, in Alzheimer’s disease (AD) brains, where diseased Tau disrupts the microtubule cytoskeleton, Tak1 and the ortholog of Drosophila IK2, Tank binding kinase 1 (Tbk1), are seen phosphorylated and colocalise with diseased Tau." (PMID 35474685, 2022).
Autoimmunity (8 papers, 2015 to 2025). The occurrence of an immune reaction against the organism's own cells or tissues. "Mutations in TBK1 have been implicated in several central nervous system diseases, and TBK1 has been tied to autoimmune functions, where it regulates immune tolerance in dendritic cells by suppressing autoimmunity." (PMID 40738190, 2025). "Here we show that T-cell-specific ablation of the kinase TBK1 promotes T-cell activation but causes retention of effector T cells in the draining lymph node in a neuroinflammatory autoimmunity model, experimental autoimmune encephalomyelitis (EAE)." (PMID 25606824, 2015). "Relative to autoimmunity, TBK1 has been shown to promote immune tolerance, at least partly through controlling dendritic cell functions." (PMID 30223576, 2018). "Work from Sun and colleagues showed that TBK1 functions in dendritic cells to regulate immune tolerance and to suppress autoimmunity." (PMID 30223576, 2018). "In the present study, we employed a conditional Tbk1-KO approach and demonstrated an unexpected role for TBK1 in the regulation of T-cell function and autoimmunity." (PMID 25606824, 2015). "Here the authors show that TBK1 is necessary for activated T-cell egress from the lymph node, and blocking TBK1 ameliorates autoimmunity in a mouse model of multiple sclerosis." (PMID 25606824, 2015). "Since the reduced threshold of T-cell activation often promotes autoimmunity, we examined the role of TBK1 in regulating a T-cell-dependent autoimmunity, EAE." (PMID 25606824, 2015). "TBK1 regulates autoimmunity, at least partly through control of dendritic cell function." (PMID 30223576, 2018). "Finally, we discuss the therapeutic potential of TBK1 inhibition in autoimmunity." (PMID 29559975, 2018). "Further studies of TBK1’s role in cellular autophagy and metabolism in various immune contexts could allow manipulation of immune function—either for protection against pathogens or rewiring toward tolerance in autoimmunity." (PMID 29559975, 2018). "Interestingly, TBK1 upregulation has been observed in PBMCs from patients with SLE and inhibition of TBK1 activity suppresses IFN-I induced autoimmunity in a mouse model of SLE." (PMID 29321042, 2018). "Understanding how TBK1 signals in TFH, how it affects cell fate decisions in T helper cell polarization, positioning and migratory pathways may provide new therapeutic strategies, especially for antibody-mediated autoimmunity." (PMID 29559975, 2018). "Finally, in patients with ambiguous diagnoses of human autoimmunity featuring elevated IgG4 and sicca symptoms, TNIP1-mediated disease may be present and would pave the way for pathway-targeted treatments such as TLR7 and TBK1 inhibitors." (PMID 39060650, 2024).
glioma (8 papers, 2016 to 2025). A benign or malignant brain and spinal cord tumor that arises from glial cells (astrocytes, oligodendrocytes, ependymal cells). "CLOCK-BMAL1 complex in glioma stem cells leads to the upregulation of periostin (POSTN) that ultimately activates the TANK-binding kinase 1 (TBK1) in endothelial cells." (PMID 38994360, 2024). "KIN001−135 is a small-molecule inhibitor for multiple targets including TANK binding kinase 1, and is under preclinical trials for glioma treatment." (PMID 36845382, 2023). "We used C16 and a TBK1 inhibitor (Bx795) to test possible mechanistic relations of these distinct innate networks in infected M059J glioma cells." (PMID 35652592, 2022). "We found that Chek2 inhibition/depletion resulted in activation of the STING pathway, as marked by the phosphorylation of TBK1 and upregulation of PD-L1 surface levels in GL261 and NPA glioma cell lines." (PMID 36949040, 2023). "Our data showed that ectopic expression of RIG-I, MDA5, MAVS, or TBK1 was not sufficient to inhibit the elevated replication of VSVΔ51 induced by D2HG in glioma cells." (PMID 37880243, 2023).